ATM (ATM serine/threonine kinase)
Diseases named in the same sentence as ATM in open-access papers (continued):
Sharing a sentence is not in itself a finding about the gene and the disease.
ataxia telangiectasia (continued). "Another study described a group of children with rheumatoid arthritis who showed a decrease in ATM expression and a skewed B cell receptor repertoire, similar to the repertoire of patients with ataxia telangiectasia." (PMID 39917433, 2024). "Cells from ataxia telangiectasia patients, which harbor mutations in ATM, display elevated MMEJ activity, suggesting that ATM suppresses MMEJ65." (PMID 38906885, 2024). "Individuals homozygous or compound heterozygous for a germline ATM PV develop ataxia telangiectasia." (PMID 38339330, 2024). "One of the first significant discoveries was the identification of the ATM gene, which is crucial in Ataxia-Telangiectasia, a disorder marked by increased sensitivity to ionizing radiation." (PMID 40191738, 2024). "STK11, PTEN, and ATM are implicated in syndromes like Peutz-Jeghers syndrome (PJS), Cowden syndrome (CS), and Ataxia–Telangiectasia (Louis-Bar Syndrome) respectively." (PMID 39390525, 2024). "The high incidence of lymphoid malignancies in those with Ataxia Telangiectasia, in conjunction with the frequency of somatic ATM aberrations described previously, is supportive of the notion that ATM acts a tumor suppressor in hematological cancers." (PMID 38347838, 2024). "The increased vulnerability of cerebellar neurones to degeneration compared to cerebral neuronal populations in individuals with ataxia telangiectasia implies a specific importance of intact ATM function in the cerebellum." (PMID 37120494, 2024). "ATM is involved in ataxia telangiectasia, a rare disease inherited in an autosomal recessive pattern." (PMID 38339330, 2024). "Although previous studies have shown that NF-κB activation depends on ATM activation, other studies have found that cells from ATM-knockout mice and individuals with ataxia telangiectasia (AT) exhibit constitutive activation of NF-κB." (PMID 39033176, 2024). "ATM (OMIM 607585) encodes the PI3K-related serine/threonine protein kinase comprising 3,056 amino acids, ataxia-telangiectasia mutated." (PMID 36865800, 2023). "A serine/threonine kinase that belongs to the phosphatidylinositol 3-kinase (PI3K)-related protein kinase (PIKK) family, ataxia telangiectasia mutated (ATM), is mutated in the uncommon human disease ataxia-telangiectasia (A-T)." (PMID 36650267, 2023). "The importance of ATM activity in DSB repair is illustrated by the fact that cells from Ataxia Telangiectasias (AT) patients exhibit marked chromosomal instability and sensitivity to radiation and other DNA damaging agents." (PMID 36656721, 2023). "In agreement with our observations, cells from subjects with ataxia-telangiectasia and knockout of ATM in mice and cells show mitochondrial dysfunction." (PMID 37932830, 2023). "Shiloh has also pointed out that ATM not only plays a role in genomic instability but also plays a role in the cerebellar degeneration of ataxia telangiectasia (AT)." (PMID 37511215, 2023). "The ATM:c.5763-1050A>G was proven to create incomplete splicing damage, which results in mild ataxia-telangiectasia phenotype in homozygous carriers." (PMID 35806449, 2022). "AT is a rare genetic disease characterized by progressive neurodegeneration, cancer predisposition, and premature aging caused by recessive mutations in the ataxia telangiectasia mutated (ATM) gene." (PMID 36207339, 2022). "Ataxia-telangiectasia (A-T), also known as Louis-Bar syndrome (OMIM #208,900), is an autosomal recessive disorder caused by mutations in the ataxia telangiectasia mutated (ATM) gene encoding a serine/threonine-protein kinase (ATM)." (PMID 34628594, 2022). "The patients with ATM predominantly presented ataxia/telangiectasia (46.2%) and infections (32.1%), while allergy (52.6%) and infection (94.4%) were the dominant first manifestations in STAT3 (AD-LOF) and DNMT3B/ZBTB24 mutations, respectively." (PMID 36544766, 2022). "Pathogenic variants in the ataxia telangiectasia mutated gene (ATM) are the cause of AT." (PMID 35163129, 2022).
ataxia telangiectasia (continued). "Nine patients with ataxia-telangiectasia were analyzed—all had defects in the ATM gene and presented with neurological defects and telangiectasia." (PMID 35729272, 2022). "ATM was first discovered in patients suffering from ataxia-telangiectasia (A-T), an autosomal-recessive genetic disease characterized by dilated blood vessels, neurodegeneration, immunodeficiency and predisposition to certain cancers." (PMID 35721517, 2022). "AT is caused by mutations of ataxia telangiectasia mutated (ATM) that controls early steps during DNA damage response signalling and could contribute to cellular senescence." (PMID 35132494, 2022). "Genetic defects in ATM lead to ataxia telangiectasia (AT) presenting with cerebellar degeneration, severe cellular sensitivity to IR, genomic instability with a predisposition to cancer, and antibody deficiency due to impaired class switch recombination." (PMID 34716846, 2022). "Ataxia telangiectasia mutated (ATM) is a protein-coding gene that causes the autosomal recessive disease, ataxia telangiectasia." (PMID 35432334, 2022). "The in-frame deletion ATM variant (c.7638_7646del, p.Arg2547_Ser2549del) was predicted to be deleterious by PROVEAN and was classified as pathogenic for Ataxia-telangiectasia syndrome by multiple ClinVar submitters." (PMID 33917078, 2021). "The genetic causes that lead to an increase in L1 activity have been mostly studied with Rett syndrome and ataxia telangiectasia, and are associated with damage in the MEPC2 and ATM genes." (PMID 34680956, 2021). "Recently, there is growing evidence that the ATM (Ataxia-telangiectasia-mutated) and ATR (ataxia telangiectasia and Rad3-related) pathways play an important role in the positive regulation of HBV replication." (PMID 34960710, 2021). "Ataxia-telangiectasia (A-T; OMIM# 208900) is a neurological disorder of ataxia caused by biallelic mutation of ATM gene (OMIM# 607585)." (PMID 34201700, 2021). "The first ataxia-telangiectasia zebrafish model was generated with morpholinos and reproduced the role of ATM in the DNA damage response." (PMID 33917666, 2021). "For instance, ATM mutations are responsible for the development of ataxia telangiectasia (AT)." (PMID 33868589, 2021). "The main idea of the suggested adjustment of G2 assay is to mimic Ataxia telangiectasia syndrome and compare the efficiency of ATM reparation within a single patient when this pathway is “on” and caffeine-induced is “off”." (PMID 35054413, 2021). "MRE11, RAD50, and NBS1 form the MRN complex in response to DNA damage to activate ATM, a gene responsible for Ataxia-Telangiectasia (A-T)." (PMID 35153719, 2021). "Ataxia-Telangiectasia (A-T) is a rare autosomal recessive disorder, first reported in 1926, caused by a deficiency of ATM (Ataxia-Telangiectasia Mutated) protein." (PMID 33142696, 2020). "Mutations in the ATM gene alter the structure and function of the ATM protein in ataxia telangiectasia (A-T) patients." (PMID 32329754, 2020). "Ataxia telangiectasia (A-T, OMIM #208900) is an autosomal recessive syndrome caused by a mutation of the ataxia-telangiectasia-mutated (ATM) gene." (PMID 32630049, 2020). "ATM and ATR, whose loss of function leads to ataxia telangiectasia and Seckel syndrome, respectively, are the two master signaling kinases activated in response to DNA DSBs (ATM) or ssDNA stretches (ATR)." (PMID 32466131, 2020). "Biallelic inactivation of ATM induces Ataxia telangiectasia (A-T) which is an autosomal recessive disorder with cerebellar degeneration, telangiectasia, immunodeficiency and cancer susceptibility." (PMID 32155193, 2020). "Patients with Bloom Syndrome and Ataxia telangiectasia, caused by mutations in the repair proteins BLM and Ataxia telangiectasia mutated (ATM) respectively, have strong predisposition to cancer and rDNA instability." (PMID 32857853, 2020).
ataxia telangiectasia (continued). "Ataxia telangiectasia mutated (ATM) kinase is a critical DDR element which can mutate and result in an autosomal recessive genetic disease termed Ataxia Telangiectasia (A-T)." (PMID 32296682, 2020). "Ataxia telangiectasia (A‐T; MIM# 208900) is an autosomal recessive genetic disorder caused by biallelic inactivation of the ATM gene." (PMID 33376610, 2020). "Ataxia–Telangiectasia (A–T; MIM#208900) is a rare autosomal recessive multisystem disorder caused by biallelic pathogenic variants in the ATM gene (MIM#607585)." (PMID 33214630, 2020). "Functional inactivation of the ATM gene product accounts for a complex disorder with a highly complex phenotype called ataxia telangiectasia (A-T), whose estimated prevalence is of 1:40,000 to 1:100,000." (PMID 32858941, 2020). "The observation that patients affected by ataxia-telangiectasia are extremely sensitive to ionizing radiation has provided the rationale to assess the role of ATM genetic variation on normal tissue radiosensitivity." (PMID 31756226, 2019). "It was reported that unrepaired DNA lesions due to ATM dysfunction in ataxia-telangiectasia patients resulted in spontaneous type I interferon (IFN) responses in humans." (PMID 30755715, 2019). "Among these genes are those coding for the protein kinases ATM (Ataxia-telangiectasia mutated) and ATR (Ataxia telangiectasia and Rad3-related), mutated in the genetic-instability syndromes Ataxia Telangiectasia and Seckel syndrome, respectively." (PMID 30995915, 2019). "Mice deficient in ataxia telangiectasia mutated (ATM), the kinase mutated in ataxia telangiectasia, have increased activation of JNK in macrophages, insulin resistance, hypertension, and increased atherosclerosis." (PMID 31384309, 2019). "For example, miR‐421 and miR‐18a target ATM, with miR‐421‐induced ATM downregulation recapitulating radiation sensitivity similar to that seen in Ataxia telangiectasia (A‐T) patients." (PMID 29845714, 2018). "Deletions of exon 63 or exons 62–63 of the ATM gene have previously been reported in patients with ataxia telangiectasia and are considered to be functionally relevant." (PMID 30086788, 2018). "We generated ATM heterozygous knock-out (ATM+/−) cell clones as a carrier model of a radiation-hypersensitive autosomal-recessive disorder, ataxia-telangiectasia (A-T)." (PMID 28729543, 2017). "Central components of the DDR machinery are the phosphoinositide 3-kinase related kinases ATM (Ataxia-telangiectasia-mutated) and ATR (ataxia telangiectasia and Rad3-related)." (PMID 29137119, 2017). "Ataxia telangiectasia (AT) patient-derived AT cells, which lack a functional ATM, are sensitive to ionizing radiation (IR) or radiomimetic agents with DNA-modifying effects." (PMID 26824362, 2016). "For example, ATM is required for phosphorylation and full activation of AKT in response to radiation-induced damage, validated in a range of cell lines including fibroblasts derived from ATM knock-out mice and patients with ataxia telangiectasia." (PMID 27527858, 2016). "H2AX is a direct substrate for phosphorylation by the host cell kinases ATM (ataxia telangiectasia mutated) and ATR (ataxia telangiectasia and Rad3-related), which along with DNA-PK are the central signaling proteins of the DNA damage response pathway." (PMID 26817608, 2016). "We confirmed these observations on human fibroblasts derived from an ataxia telangiectasia (AT) patient, which have impaired ATM signalling." (PMID 26848154, 2016). "Premature ageing syndrome genes ATM (ataxia-telangiectasia), DKC (dyskeratosis congenita) and WRN (werner syndrome) all exhibited lower transcript abundance in older individuals, concordant with loss-of-function alterations in disease-related mutations." (PMID 26490707, 2015).
ataxia telangiectasia (continued). "The best-studied PSs are Werner Syndrome (WS), Ataxia Telangiectasia (AT) and Hutchinson Gilford Progeria (HGPS), which carry causal mutations in the WRN RecQ helicase, ataxia telangiectasia checkpoint kinase ATM, and lamin A/C respectively." (PMID 25214013, 2015). "ATM-independent senescence has been shown in primary fibroblasts derived from patients with ataxia-telangiectasia and was induced by p38 activation." (PMID 25649709, 2015). "Diagnosis of Ataxia-Telangiectasia (A-T) was confirmed by molecular analysis of ATM gene and by the evidence of ATM protein absence by western blot analysis." (PMID 25881033, 2015). "We sequenced the ATM coding region using mRNA isolated from LCLs derived from ten ataxia-telangiectasia patients of Mennonite ethnicity and identified the missense variant c.6200C>A (p.A2067D) in each." (PMID 25077176, 2014). "Using caffeine, a PI3 kinase-like inhibitor, KU 55933, an ATM-specific inhibitor, AT cells derived from patients with ataxia telangiectasia, or siRNAs to deplete ATM, results in reduced or blocked HCMV replication." (PMID 24859341, 2014). "Linkage analysis detects that ATM gene located on chromosome 11q22–23 transcripts mRNA with a coding sequence of 9168 bp, and it is responsible for ataxia telangiectasia, an autosomal recessive inheritance disorder." (PMID 25541996, 2014). "Ataxia telangiectasia mutated (ATM), a protein involved in the DDR is mutated in the syndrome ataxia telangiectasia (AT)." (PMID 24795863, 2014). "Together, these data identify a distinct role for ATM during the formation/resolution of neural Top1-CCs and suggest that their accumulation contributes to the neuropathology of ataxia telangiectasia." (PMID 23626666, 2013). "The ataxia-telangiectasia mutated (ATM) (OMIM 607585) gene, a key player in the DDR, is mutated in the autosomal recessive disorder ataxia-telangiectasia (AT, OMIN number 208900)." (PMID 24159334, 2013). "These are similar findings to those in the murine model of Ataxia telangiectasia (ATM), which also demonstrated significant impairment of stem cell populations at least partially due to ROS and oxidative stress." (PMID 22701784, 2012). "Increased radiosensitivity has been found in cells from patients with DDR or DNA-repair disorders such as Ataxia Telangiectasia (defect in ATM), Nijmegen Breakage Syndrome (defect in NBS1), Fanconi anemia, defective Artemis, DNA ligase I and DNA ligase IV." (PMID 20846433, 2010). "ATM, a protein defective in the heritable disorder, ataxia telangiectasia, is a central signaling kinase in the response to double strand breaks and is involved in the regulation of cell cycle checkpoints." (PMID 18509505, 2008). "For example, mutation of the upstream kinase ATM, which is mutated in ataxia telangiectasia (AT), impairs HR and NHEJ, although it is yet unclear whether these alterations underlie the pronounced radiation hypersensitivity of AT cells." (PMID 15054444, 2004). "Using both plasmid and adeno-associated virus (AAV) donor vectors, our results demonstrate that ataxia telangiectasia and Rad3-related kinase (ATR) activity is essential for knock-in regardless of the donor type, whereas ataxia telangiectasia mutated (ATM) inhibition exhibits a donor-dependent role." (PMID 41651998, 2026). "The Ataxia Telangiectasia Mutated (ATM) protein kinase is a well recognized master regulator of the DNA damage response (DDR) and cell cycle control whose dysfunction leads to the rare neurological disorder Ataxia Telangiectasia (AT)." (PMID 42064813, 2026). "Genetic disorders such as ataxia-telangiectasia (AT) and Nijmegen breakage syndrome result in extreme radiosensitivity due to defects in key DDR proteins such as ataxia-telangiectasia-mutated kinase (ATM) and nibrin (NBN)." (PMID 40282189, 2025). "In summary, this study suggests that ATM and p-ATM protein expression may have clinical implications for prognostic evaluation and the severity of ataxia telangiectasia symptoms." (PMID 39853455, 2025).
ataxia telangiectasia (continued). "Unlike the germline ATM mutations seen in ataxia‐telangiectasia (A‐T), which typically present as truncating/deleterious mutations, somatic ATM mutations exhibit a broader range, including various missense mutations with variable clinical significance." (PMID 40622001, 2025). "Data analysis confirms that the severity of Louis-Bar syndrome is determined not solely by the type of ATM mutation, but also by a combination of genetic and epigenetic factors." (PMID 41451872, 2025). "Since the detection rate of biallelic pathogenic variants is extremely low, including ataxia telangiectasia for ATM and Fanconi anemia for BRCA1 and BRCA2, we did not describe the autosomal recessive mode of inheritance in the Fact Sheet, except for MUTYH." (PMID 40183848, 2025). "Indeed, ataxia telangiectasia (AT) patients deficient in ATM have an increased risk of developing multiple cancers, including T-cell acute lymphoblastic leukemia (T-ALL), a malignancy arising from T-cell precursors arrested at various stages of thymic development." (PMID 39637056, 2024). "In 1995, the ATM gene was discovered and was found to be responsible for ataxia–telangiectasia." (PMID 39543654, 2024). "Examination of the NF-kB activation pathway in ataxia telangiectasia (AT) cell mutants of the ATM gene showed that after irradiation, AT cells do not degrade IκB-α and exhibit reduced NF-kB binding activity; however, ATM WT overexpression restores radiation-induced degradation of IκB-α." (PMID 38534394, 2024). "Considering the syndromes predisposing to prostate cancer, several overlaps with breast or ovarian cancer syndromes emerge: BRCA1- and BRCA2-associated hereditary cancer syndrome (gene: BRCA1/2), ATM or AT or Louis-Bar syndrome (gene: ATM), and Lynch syndrome (LS) (lft 5–16%)." (PMID 37239385, 2023). "The intronic expansion in FXN (Friedreich ataxia), results in the decreased expression of frataxin, a protein involved in mitochondrial iron metabolism, and the ATM protein (ataxia–telangiectasia) is a powerful protein cinase, involved in the cellular response to genotoxic stress." (PMID 37048110, 2023). "Cells from ataxia telangiectasia (AT) patients lack ATM and accumulate chromosomal alterations." (PMID 38021281, 2022). "The absence of ATM is the cause of a rare autosomal recessive disorder called Ataxia Telangiectasia characterized by cerebellar degeneration, telangiectasia, immunodeficiency, cancer susceptibility, and radiation sensitivity." (PMID 34771661, 2021). "Ataxia Telangiectasia (A-T) and Ataxia with Ocular Apraxia Type 1 (AOA1) are devastating neurological disorders caused by null mutations in the genome stability genes, A-T mutated (ATM) and Aprataxin (APTX), respectively." (PMID 34723800, 2021). "Defects in ATM give rise to ataxia-telangiectasia (AT) (OMIM #208900)." (PMID 32648006, 2020). "Following DNA damage, activation of the serine/threonine kinases, ATM (ataxia-telangiectasia mutated) and ATR (ataxia telangiectasia and Rad3-related), termed DNA sensors, may occur." (PMID 35582576, 2019). "Ataxia-Telangiectasia (A-T) is a rare, recessive disease characterised by the absence of Ataxia-Telangiectasia Mutated (ATM) protein kinase." (PMID 30886180, 2019). "TRIM29, also known as Ataxia-telangiectasia group D, was identified for its capacity to induce resistance to ionizing radiation (IR) in cells derived from patients with ataxia telangiectasia, a disorder characterized by ATM (Ataxia Telangiectasia-Mutated) deficiency." (PMID 30974870, 2019). "Interestingly, AT is caused by mutations affecting serine-protein kinase ATM (ataxia telangiectasia mutated), a pVHL interactor of unknown binding interface." (PMID 30943211, 2019). "Ten of them were diagnosed with ataxia telangiectasia, of whom six were confirmed to have ATM mutations while no genetic testing was attempted for the other four patients." (PMID 30697212, 2018). "Dysfunction of ATM results in ataxia-telangiectasia (AT) in humans." (PMID 30057676, 2018).